WNT3A (Wnt family member 3A)
Diseases named in the same sentence as WNT3A in open-access papers (continued):
Sharing a sentence is not in itself a finding about the gene and the disease.
tumor (continued). "Inactivation of the Wnt7b gene blocks the soft agar outgrowth of tumour cells to the same extent as addition of C59 and again this can be largely rescued by WNT3a conditioned medium." (PMID 30926782, 2019). "In these malignant tumors, Wnt3a expression is closely related to tumor growth, metastasis, chemo- / radio- resistance and maintenance of CSC characteristics." (PMID 31528227, 2019). "The expression levels of Wnt2B, Wnt3A, Wnt6, Wnt8B and Wnt10B were significantly higher in primary liver tumor tissues than which in adjacent non-tumor tissues." (PMID 30814912, 2019). "Previous studies have found that Wnt3a can mediate Wnt signaling pathway activation by both autocrine and paracrine signaling loops in the tumor microenvironment (TME)." (PMID 31528227, 2019). "Collectively, our results suggested that the dynamic interaction of PSPC1 or PSPC1-Y523F with PTK6 or β-catenin modulated autocrine Wnt3a/β-catenin signaling to synergize tumor progression in HCC." (PMID 31844057, 2019). "Next a scratch test was performed to check if ß-catenin inhibitors or WNT3A influence the migratory abilities of the tumor cells." (PMID 30568936, 2018). "Western blot analysis showed that Wnt3, Wnt3a and Wnt10a were indeed expressed in the tumor grafts, and their expression levels were higher than those in normal subcutaneous tissue and normal mouse colon." (PMID 28147310, 2017). "The expression levels of Wnt3a were downregulated in tumor nodules injected by miR-491 lentivirus-infected cells compared to negative control lentivirus-infected cells, which was similar to the results in GC cell lines." (PMID 28358374, 2017). "Consistent with the suppression of β-catenin and Wnt3A, we conclude that anti-proliferative effects of itraconazole on tumor cells are facilitated by modulating Wnt3A and β-catenin, and negatively regulate gene Axin-1." (PMID 28212537, 2017). "To address this question, we performed intravenous injection of GFP-labeled, PTENWT WNT3A overexpression cells and monitored metastatic tumor formation in lung tissue." (PMID 28092677, 2017). "To further demonstrate that miR-491-5p inhibits tumor progression through targeting Wnt3a, we constructed rescue experiments." (PMID 28358374, 2017). "Co-overexpression of Wnt3a and miR-ctrl or miR-491 in MKN45/SGC-7901 cells showed that Wnt3a overexpression reduced the tumor-suppressing effect of miR-491-5p on GC cell proliferation." (PMID 28358374, 2017). "As expected, in vivo data showed that the expression of Wnt3a in tumor tissues was reduced in miR-491-treated tumors by western blot." (PMID 28358374, 2017). "Western Blot analysis were used to investigate the crucial molecules involved in selected signaling pathways associated with apoptosis (caspase-9 and PARP-1), cell survival (ERK 1/2) and tumor progression (Wnt3a and β-catenin)." (PMID 27367907, 2016). "Consistently, previous studies have revealed multiple targets for miR‐16 including BCL2, CCND1 and WNT3A 17, 18, 19, 20, which are involved in tumour cell apoptosis or cell‐cycle regulation; and thus, directly regulate tumour growth." (PMID 27241533, 2016). "In multiple tumor types, WNT3a is capable of promoting the proliferation of tumor cells via canonical WNT/β-catenin signaling." (PMID 27391060, 2016). "Accumulating evidence has suggested that Wnt3a promotes or suppresses tumor progression via the canonical Wnt signaling pathway depending on cancer type." (PMID 26369691, 2015). "Wnt3a overexpressing cells grew into larger tumor masses compared with the control cells (p < 0.05)." (PMID 26266404, 2015). "The mouse xenograft model showed that Wnt3a-overexpressing cells grew into larger tumor masses and formed more VM than the control cells." (PMID 26266404, 2015).
tumor (continued). "As the enzyme primarily responsible for the degradation of HS chains, heparanase has been shown to modify tumor cell responses to HS-binding of Wnt3a such as effects on cell proliferation and adhesion, in addition to its HS-chain degrading activity." (PMID 25669977, 2015). "Wnt3a-expressing H929 cells injected into human bone exhibit increased osteoblast-to-osteoclast ratios and therefore reduce tumor burden." (PMID 26369691, 2015). "In the present study, wnt3a expression was significantly correlated with MMP-9 expression in the primary tumor, mesenchyme and metastatic site." (PMID 24564183, 2014). "Wnt3a and wnt5a expression had a concordance rate higher than 60% with a high concordance rate between the primary tumor and metastatic site." (PMID 24564183, 2014). "We also found that Wnt3a has significant stimulative effects on tumor growth and metastasis in nude mice." (PMID 25499541, 2014). "Wnt3a expression in the primary tumor was significantly correlated with lymph node involvement (p = 0.038) and MMP-9 expression in primary, adjacent mesenchyme and metastatic sites (p = 0.038, 0.022 and 0.004, respectively)." (PMID 24564183, 2014). "Several positive-acting ligands for this pathway, including Wnt3, Wnt3a, Wnt7b, and Wnt5a, are significantly overexpressed in tumor tissue, and mRNA for Wnt3 is about 5-fold more abundant in transgenic mammary tissue than in non-transgenic mammary tissue." (PMID 21304988, 2011). "We further demonstrated that cells transduced with core and Wnt3A exhibited increased proliferation, promoted cell cycle progression and accelerated tumor formation in athymic nude mice." (PMID 22110662, 2011). "Exogenous core expression was shown to enhance Wnt3A-stimulated HCC tumor growth, possibly by inducing β-catenin accumulation and oncogene overexpression." (PMID 22110662, 2011). "Co-expression of core and Wnt3A in HCC cells leads to an accelerated tumor formation in athymic nude mice." (PMID 22110662, 2011). "All mice injected with core, Wnt3A plus GFP or Wnt3A plus core formed xenograft tumors within 6 weeks after inoculation, and tumor sizes in mice injected with Wnt3A and core co-infected cells were much larger than that of either core or Wnt3A alone (p<0.01)." (PMID 22110662, 2011). "The results of this study support our previous findings, and those of others, that increased bone mass resulting from exogenous MSC cytotherapy or treatment with DKK1-neutralizing antibody, Wnt3a, or lithium chloride negatively impact MM tumor burden in bone." (PMID 21188144, 2010). "Implantation of Wnt3A-expressing tumor cells into mice led to decreased tumor growth and metastasis when compared to controls." (PMID 24281103, 2010). "Furthermore, our results indicate that PF-309 inhibits key signaling pathways involved in CRC progression, including the mTOR, p70 S6K, EIF4G1, NF-κB, IKB-α, c-Myc, WNT3A, and β-catenin pathways, underscoring its broad spectrum of anti-tumor effects." (PMID 41459112, 2026). "To validate whether DPP7/WNT3A/β‐catenin pathway is essential for the anti‐tumour effect of Tamarixetin, we examined the proliferation of DPP7 overexpressing cells after the treatments." (PMID 40845164, 2025). "Based on the biological feature, we employed a Wnt3a-free culture system to selectively promote the outgrowth of tumor organoids while limiting the expansion of normal colonic epithelium, which is otherwise highly dependent on Wnt3a and proliferates more rapidly." (PMID 41045935, 2025). "Furthermore, ITZ was found to downregulate tumor markers such as Ki-67 and key components of the Wnt/β-catenin signaling pathway, including Wnt-3a and β-catenin, while upregulating Axin-1 expression." (PMID 40697374, 2025). "Furthermore, non-coding RNAs (e.g., LINC00665 and circ0000670) contribute significantly to tumor progression by interacting with critical molecules within the Wnt pathway (such as Wnt3a and HMGB1)." (PMID 40951343, 2025).
tumor (continued). "WNT3 is probably involved in the development of drug resistance of MM cells by an autocrine mechanism, and WNT3A may contribute to the proliferation of tumor cells." (PMID 40650009, 2025). "On the other hand, some Wnt ligands (i.e., Wnt3a) released into the tumor microenvironment could be produced by both CCA and inflammatory cells." (PMID 37512809, 2023). "Indeed, Wnt3a is involved in several processes, including tumor cell proliferation, migration, and tumor angiogenesis." (PMID 37407689, 2023). "In addition, blockade of either sICAM‐1 or WNT3A diminishes the harmful effect of radiation on tumor progression." (PMID 34813169, 2022). "A mouse xenograft model showed that high Wnt3a expression led to larger tumor masses and more VM." (PMID 36072972, 2022). "Taken together, these results suggest that sICAM‐1, which is elevated upon radiation, acts as a chemoattractant that entices macrophages into tumor‐microenvironment and stimulates these macrophages to secrete WNT3A, which in turn induces the transition of GBM into the mesenchymal state." (PMID 34813169, 2022). "In addition, FTO expression levels were inversely correlated with Wnt-3a levels in tumor tissues, further supporting the role of the activated Wnt/β-catenin signaling in the repression of FTO." (PMID 33966037, 2021). "In contrast, the Apc deficient tumor organoids can survive in the media lacking R-spondins and Wnt3a, since tumor cells carry bi-allelic inactivation of Apc, which causes ligand-independent constitutive activation of Wnt signaling." (PMID 34262603, 2021). "Knocking down Wnt-1 and Wnt-3A suppresses tumor proliferation." (PMID 33262947, 2020). "We, therefore, explored whether inducing Wnt3a overexpression in LLC cells might have a similar impact to anti-tumor responses, as Wnt1." (PMID 30926812, 2019). "Besides, silencing Wnt3a inhibited cancer cells proliferation in vitro and significantly suppress tumor growth in vivo." (PMID 31737122, 2019). "In addition, a reduction of Cdk6 transcripts is observed in Wnt7b knockout tumour cells, which can be restored by WNT3a supplementation." (PMID 30926782, 2019). "6‐10B cells transfected with control or Wnt3a cDNA were used to establish xenograft tumours." (PMID 31111621, 2019). "In addition, we tested sphere formation ability of all three RMS tumor cell lines after a 48 h pretreatment with the inhibitors (due to toxicity of FH535) or a 96 h pretreatment with WNT3A (to induce muscle differentiation)." (PMID 30568936, 2018). "Moreover, overexpression of Wnt3a substantially reversed the tumor-suppressive effects of miR-491-5p on cell proliferation and apoptosis in a rescue experiment." (PMID 28358374, 2017). "Importantly, quantification of the tumor burden in the lungs was found to be significantly reduced in the WNT3A overexpression treated animals." (PMID 28092677, 2017). "Furthermore, Wnt3a has been reported to be upregulated in human cancers, and involved in tumor growth and metastasis." (PMID 28358374, 2017). "Once SALL4 was activated, it may trigger downstream target gene Wnt3a to promote tumor progress and metastasis." (PMID 27329034, 2016). "Wnt3a stimulation promoted tumor initiation only in HM20 cells." (PMID 26075748, 2015). "Other studies have shown that Wnt3a serves as a tumor suppressor based on two main findings." (PMID 25499541, 2014). "Wnt3a expression in primary tumors was significantly associated with lymph node involvement (p = 0.038) and MMP-9 expression in the primary tumor (p = 0.0387), mesenchyme adjacent to tumor (p = 0.022) and metastatic site (p = 0.004)." (PMID 24564183, 2014). "Also, core protein increases cell proliferation rate and promotes Wnt3A-induced tumor growth in the xenograft tumor model of human HCC." (PMID 22110662, 2011). "Taken together, these data show that FZC18 may interact with Wnt3a, suggesting that FZC18 may function as a SFRP-like bioactive polypeptide quenching at least Wnt3a in the tumor microenvironment." (PMID 18382662, 2008).
tumor (continued). "Furthermore, research has indicated that Wnt3a is a tumor suppressor." (PMID 39200196, 2024). "Moreover, this research further verified that the SLIT3/UBE2C axis could mediate tumor cell proliferation and migration via Wnt3A/β-catenin signaling pathway activation." (PMID 39479352, 2024). "Moreover, both PN and IL17A increase WNT3A secretion indicating that WNT3A signaling may have a crucial role in tumor cellular hierarchy." (PMID 35982950, 2022). "Finally, LINC00662 promotes HCC tumor growth and metastasis via upregulating WNT3A." (PMID 31785055, 2020). "The up-regulated levels of Wnt3a expression in sera of HCC patients was closely associated with HBV infection (P<0.001), lymph node metastasis (P=0.016), differentiation degree (P=0.001), TNM staging (P=0.003), Child-pugh classification (P<0.001), and tumor recurrence (P=0.014)." (PMID 31737122, 2019). "To analyse whether the results obtained in CCD-18Co cells can be extended to other colon fibroblasts, we studied the effects of 1,25(OH)2D3 and Wnt3A in primary cultures of paired NFs and CAFs derived from colon healthy tissue or primary tumours, respectively, of CRC patients." (PMID 31147591, 2019). "However, the role of Wnt3a in the tumor microenvironment is not fully understood." (PMID 31528227, 2019). "PSPC1 upregulation or PSPC1-Y523F mutation loses nuclear sequestration of tumor suppressive PTK6 to promote cancer EMT, stemness and metastasis via oncogenic cytoplasmic translocation of PTK6 and nuclear translocation of β-catenin, which interacts with PSPC1 to promote Wnt3a autocrine signaling." (PMID 31844057, 2019). "However, we here found that WNT3A slightly reduced the migration rate of RMS tumor cells." (PMID 30568936, 2018). "Moreover, Wnt3a or LiCl treatment boosted macrophages to polarize to M2 macrophages under an inflammatory stimulus, and knockdown of β-catenin in M2 macrophages abolishes the functions of TAMs when co-cultured with tumor cells." (PMID 30022048, 2018). "We found there was reduced tumor burden in the lungs of mice injected with the WNT3A overexpression cells compared with control cells, where distinct areas of metastatic-free tissue could be observed in the WNT3A animals compared with control lungs." (PMID 28092677, 2017). "It has been shown that the inhibitor of the DKK1 pathway can suppress WNT3A-dependent OPG expression in osteoblasts, impairing osteogenesis, and artificial stimulation of WNT3A in MM can enhance osteogenesis and reduce tumor growth." (PMID 40650009, 2025). "Combined expression of WNT ligands (WNT3A, WNT4, WNT7B, WNT9A, WNT10A, WNT11) in BRCA patient tumours has a positive correlation (R = 0.27, p value = 0) with the combined expression of key EMT-inducing transcription factors SNAI1, SNAI2, ZEB1, ZEB2 and TWIST1." (PMID 38678032, 2024). "This class is known as a tumor suppressor and works by targeting the BCL2,MCL1, CCND1, and WNT3A genes." (PMID 38530760, 2024). "These are percentages of deaths according to the variable age at diagnosis, gender, metastases, tumor site, ABCB5, WNT3A, and OPN markers, andp-values from statistical tests." (PMID 39239573, 2024). "LINC00662 activates the Wnt/β-catenin signaling pathway in HCC cells in an autocrine manner by inducing WNT3A secretion, further promoting HCC cell proliferation, cell cycle, and tumor cell invasion, while inhibiting HCC cell apoptosis." (PMID 37056336, 2023). "Wnt3a/β-catenin, circSATB2, HIF-1α/COX-2, and LMO7 in tumor-derived EV modulate genes or signaling pathways promoting the successful proliferation and migration of tumor cells." (PMID 36829523, 2023). "HCV core protein can reduce E-cadherin expression levels due to CDH1 gene promoter hypermethylation, with consequent dissociation of the β-catenin/E-cadherin complex, and stimulates tumor cell growth by GSK-3β inactivation and Wnt3a release." (PMID 37512809, 2023).
tumor (continued). "Androgen-signaling inhibition elevated Wnt2, Wnt3a, and Wnt5a expression in CAF, and enhanced tumor epithelial cell survival." (PMID 35884514, 2022). "Consistent with cell experiments, miR-374b-5p expression was upregulated in EOC tumor tissues by GLA treatment, whereas the levels of HMGB3, Wnt3a, and β-catenin were downregulated (P < 0.05)." (PMID 35912216, 2022). "Tumor-bearing mice in the TB-G-N group showed markedly lower levels of p-EGFR, TGF-β, p-AXL, Wnt3a, and β-catenin proteins compared to those in the TB-G group." (PMID 36547898, 2022). "Second, Wnt signaling, where, in cultured tumor cells, TNC binds to the Wnt3a ligand, thus either promoting (when TNC and Wnt3a are offered as substratum) or inhibiting Frz signaling (when offered as soluble molecules)." (PMID 36102918, 2022). "Administration of neutralizing antibodies for PN, or WNT3A, or IL17A, or CD44v6 increased the efficacy of FOLFOX-chemotherapy on reducing tumor growth." (PMID 35982950, 2022). "Note that the basal tumorigenic activity of SW480-FR-CICs was much higher compared to SW480-S-CICs, and treatment with each of the three stromal-secreted factors (PN, WNT3A and IL17A) increased tumor sphere formation ability relative to vehicle treated CICs." (PMID 35982950, 2022). "Acting as a paracrine factor, tumor‐derived sICAM‐1 induces macrophages to secrete wingless‐type MMTV integration site family, member 3A (WNT3A), which promotes a mesenchymal shift of GBM cells." (PMID 34813169, 2022). "miR-15a and miR-16 act as tumor suppressors: they downregulate multiple oncogenes (BCL2, MCL1, CCND1, and WNT3A), decreasing PC cell survival, proliferation, invasion, and EMT by targeting TGF-β signaling." (PMID 34830196, 2021). "Several studies reported that TQ suppressed tumor progression via PI3K/Akt and Wnt3a pathways in various types of cancer." (PMID 33663486, 2021). "In the circ0101675 knockdown group, the WNT3A and WNT5A expression was significantly reduced in tumor tissues." (PMID 34093821, 2021). "The transcription-related protein FRA1 was shown to act downstream of WNT3A signaling, promoting EMT in GBM cells and therefore contributing to the aggressive behavior of this tumor." (PMID 33312955, 2020). "In PCa, the miR-15a/miR-16 cluster was found to suppress tumor invasion by suppressing the TGF-β signaling pathway to inhibit growth through CCND1 and WNT3A." (PMID 33614501, 2020). "miR-15a/16 exerts tumor suppressive roles by targeting multiple oncogenes, including BCL2, TWIST1, MCL1, CCND1 and WNT3A." (PMID 32678069, 2020). "Based on the quantitative reverse transcription-polymerase chain reaction (RT-PCR), the increase in the mRNA expression of Wnt3a, Wnt5a and Wnt7b has been shown in the CCA tissues in comparison with non-tumor tissues." (PMID 32140709, 2020). "On the other hand, Annavarapu and colleagues described that WNT3A-driven activation of ARMS and ERMS cell lines through key components of the canonical WNT/β-catenin pathway had tumor suppressive function at least in ARMS." (PMID 30568936, 2018). "The results showed tumor volume growth in the control group (injected with PBS or 5-FU only), and Wnt3a significantly accelerated HCT-8 cancer cell growth under 5-FU treatment." (PMID 30111797, 2018). "Our current research highlights that SMAR1 is a substrate in the Wnt3a driven proteasomal degradation and restoration of SMAR1 inhibits tumor growth by down-modulating Wnt/β-catenin signaling activities." (PMID 29765542, 2018). "Remarkably, this CTC-subset displayed tumor stem-like features, as evidenced by the expression of key stem-like genes including Bmi1, CD44, Oct4, Notch1, Wnt3a, Stat3, and HIF-1α." (PMID 27738343, 2017). "The authors identified CD45- CD90+ CTCs in 91% of samples and demonstrated that this cell population expressed key stem-like genes including Bmi1, CD44, Oct4, Notch1, Wnt3a, Stat3, and HIF-1a compared to CD90+ tumor-tissue cells." (PMID 27738343, 2017).